CCL2 (C-C motif chemokine ligand 2)
Diseases named in the same sentence as CCL2 in open-access papers (continued):
Sharing a sentence is not in itself a finding about the gene and the disease.
diabetes (426 papers, 2005 to 2026). "Monocyte chemoattractant protein 1 (referred to in the figures as Ccl2 gene) is linked to proinflammatory states, and its renal expression was increased in diabetic mice (p = 0.018 for diabetes as a factor)." (PMID 39434906, 2024). "The analysis showed that five SNPs were associated with diabetes: rs1024611 at the CCL2 gene locus, rs6749704 at CCL20, rs333 at CCR5, rs17366743 at ADIPOQ, and rs114758349 at TCF7L2." (PMID 36674502, 2023). "One of these, CCL2 (MCP1), is documented to promote a local proinflammatory environment associated with islet death and diabetes." (PMID 28968432, 2017). "In addition, several cross-sectional observational studies showed that patients with diastolic dysfunction and/or diabetes were associated with increased IL-6, IL-8, and CCL2." (PMID 38630423, 2024). "Moreover, in a diabetes model induced by a high-fat diet, Ccl2-deficient mice are protected from development of diabetes and testicular dysfunction." (PMID 35307018, 2022). "Moreover, in the STZ- model of diabetes, induction of diabetes increased albuminuria in CCL2+/+ mice, which was significantly reduced in CCL2-deficient mice." (PMID 33692997, 2021). "Previous studies found that CCL2 levels are associated with hypertension and diabetes." (PMID 31396527, 2019). "The proinflammatory cytokine profiles in the diabetes mellitus patients, including IL-8, were correlated with severity of the course of disease and polymorphisms of pro-inflammatory cytokine genes (CCL2, TGFB1, IL8, CCR5, and MMP9) were found to be associated with the risk of diabetic nephropathy." (PMID 24386171, 2013). "Importantly, a transgenic mouse with increased expression of Ccl2 (encoding chemokine [C-C motif] ligand 2) in their beta cells developed diabetes; this is consistent with our observed age-related upregulation of Ccl2 being detrimental for endocrine pancreatic function." (PMID 26699651, 2016). "In univariable analyses, CCL2, ICH volume, diabetes, and lobar ICH were significantly associated with late SED, whereas NIHSS score at admission, ICH volume, and lobar ICH were significantly associated with early SED (p < 0.05)." (PMID 41915645, 2026). "CCL2 is elevated in many diseases, such as cancer, rheumatoid arthritis, diabetes and cardiovascular diseases." (PMID 40084478, 2025). "In diabetes, HSCs can be activated by liver injury and systemic cytokines, like IL-17 and IL-20, enhancing CCL2-mediated monocyte recruitment." (PMID 40362271, 2025). "The GSEA analysis further demonstrated the pivotal roles of CXCL8, IL1B, and CCL2 in diabetes through immune and inflammatory mechanisms." (PMID 38167125, 2024). "Gene Set Enrichment Analysis revealed that CXCL8, IL1B, and CCL2 have significant potential in diabetes." (PMID 38167125, 2024). "In contrast, in blood samples from T1DM patients, the CCL2 protein level is lower than that in control samples, but it is elevated in patients with diabetes complications." (PMID 39457105, 2024). "For example, one of the studies has shown that CCL2 was significantly correlated with standard diabetes-related parameters like glycemic excursion and HbA1c." (PMID 39457105, 2024). "CCL2 levels are elevated in various pathological conditions, including atherosclerosis, rheumatoid arthritis (RA), OA, diabetes, psoriasis, cancer, and infectious diseases, highlighting its importance in disease pathogenesis." (PMID 39076996, 2024). "Topical application of CCL2 can accelerate cutaneous wound healing in mice with diabetes by promoting neovascularization." (PMID 36609486, 2023). "CCL2, also known as MCP-1, is a proinflammatory chemokine and has a controversial role in diabetes and wound healing." (PMID 36798135, 2023). "Inhibition of CCL2 improves glucose disorder, significantly reduces the progression of diabetes complications, and improves the survival rate of islet transplantation in patients with T1DM." (PMID 36675322, 2023).
diabetes (continued). "The deletion of IL-33 enhanced diabetes-induced retinal inflammation, evidenced by upregulated pro-inflammatory cytokine expression (Ccl2, Il1b, Il6, Tnf, Tgfb and Inos), sustained gliosis and microglia activation." (PMID 37671525, 2023). "In the ethnic subgroup analysis, significant differences for diabetic nephropathy in terms of diabetes duration (≥10 years) were observed for CCL2 rs3917887, CCR5 rs1799987, ELMO1 rs74130, and IL8 rs4073." (PMID 37187702, 2023). "Among MCP family members, monocyte chemotactic protein-1 (MCP1), also known as CCL2, is the most studied chemokine in osteoarthritis (OA), diabetes and bone fracture healing fields." (PMID 35743867, 2022). "In several experimental studies, CCL2 is proposed as a potential healing target and biomarker in renal tissue-impaired patients having diabetes." (PMID 35843953, 2022). "Expressions of inflammatory cytokines in the glomeruli were assessed and showed that diabetes elevated the expressions of Ccl2, Tnfa, Il1b, Adgre1 (F4/80), and Itgam (CD11b) in both PPKM2Tg and WT mice, but they were attenuated in diabetic PPKM2Tg mice." (PMID 35133981, 2022). "We also observed inflammatory markers (IL-8, TNF-α and CCL2) protein expression was positively correlated with SRA1 protein expression in individuals with diabetes." (PMID 34685582, 2021). "MCP-1/CCL2 knockout was demonstrated to inhibit the development of albuminuria and to reduce the number of atrophic tubules promptly after diabetes onset in streptozotocin-induced diabetic mice." (PMID 33139635, 2020). "Patients treated with emapticappegol presented a trend toward reduced urinary albumin excretion and HbA1c, suggesting a promising role of this CCL2 inhibitor in both kidney disease and diabetes mellitus." (PMID 30090066, 2018). "Conversely, overexpression of CCL2 in NOD pancreatic β-cells that leads to recruitment of large numbers of monocytes to the pancreas caused insulitis and even the development of diabetes." (PMID 29742113, 2018). "For the treatment of diabetes mellitus, one Spiegelmer aptamer that targets the monocyte chemoattractant protein 1 (MCP-1 also called CCL2) is used." (PMID 27413756, 2016). "Gene expression array results indicate that although VEGF is upregulated in diabetic retinas along with other angiogenic factors like Ang-2 and TNFα, CCL2 is remarkably upregulated, and this increase is maintained at least up to 8 weeks of diabetes." (PMID 25329075, 2014). "Results from this study demonstrate that the CCL2 gene is dramatically upregulated in retinas of diabetic animals following the induction of diabetes, and this is coincident with the influx of numerous perivascular monocytes into the retinal tissues." (PMID 25329075, 2014). "The expression of CCL2 (chemokine ligand 2) was significantly up-regulated in the retinas of rats with 4 and 8 weeks of diabetes and also in human retinal endothelial cells treated with high glucose and glucose flux." (PMID 25329075, 2014). "After 4 weeks of diabetes the expression of all of these genes was significantly increased with remarkably high levels of CCL2 (15-fold increase)." (PMID 25329075, 2014). "Using CCL2 knockout (Ccl2−/−) mice, we show a significant reduction in retinal vascular leakage and monocyte infiltration following induction of diabetes indicating the importance of this chemokine in alteration of the BRB." (PMID 25329075, 2014). "Our findings demonstrate that specific chemokines are upregulated in the retinas of diabetic animals, and that the chemokine CCL2, plays an indirect role in mediating the increase in retinal vascular permeability in diabetes." (PMID 25329075, 2014). "Activated MC/MPs express inflammatory cytokines such as CCL2, TNFα, and IL-1β in experimental diabetes." (PMID 24278148, 2013).
diabetes (continued). "For example, transgenic overexpression of CCL2 in islet β-cells promotes massive immune cell infiltration into the islets and the quantity of CCL2 synthesized and secreted from β-cells into the serum correlates with diabetes development." (PMID 23056550, 2012). "Polymorphisms that increase the expression of the CCL2 gene negatively correlate with pancreatic islet function and transgenic overexpression of CCL2 specifically in islet β-cells promotes insulitis and progression to diabetes in the B6D2 genetic background." (PMID 23056550, 2012). "Diabetes also increased IL-1β and CCL2 in the kidneys, which was suppressed by VP3.15 treatment." (PMID 39880090, 2025). "Diabetes increased Ccl2 mRNA expression and protein levels in the kidneys of REDD1+/+ mice." (PMID 39920111, 2025). "Intriguingly, correlation analysis showed a significant association between PPARδ, but not CD36, and CCL2, therein implicating subclinical inflammatory potentiation of monocytic cells in patients with diabetes." (PMID 38989454, 2024). "However, 6 months after the induction of diabetes, the expression levels of Ccl2, Il1b, Il6, Tnf, Tgfb and Inos (Nos2) were significantly higher in the Il33−/− retina than in the WT retina." (PMID 37671525, 2023). "In addition, Lcn10-KO macrophages exhibit higher expression of cytokines/chemokines (i.e., IL-6, IL-1β, and CCL2) than wild-type controls, which are also major culprits for the development of cardiomyopathy during diabetes." (PMID 35757735, 2022). "In addition, pharmacological inhibitionof CCL2 was able to reduce inflammation and improve podocyte function in diabeticnephropathy 19, as well as recover kidneyfunction in patients with diabetes mellitus who experienced albuminuria." (PMID 34251390, 2022). "Indeed, targeting CCL2 and other factors secreted by senescent cells alleviated metabolic dysfunction and showed efficacy in diabetes and obesity." (PMID 32686726, 2020). "CCL2 has been demonstrated to be a potential intervention point for the treatment of diabetes." (PMID 33148888, 2020). "Therefore, this study is aimed at investigating the association of a genetic polymorphism of CCL2-rs3917887, CCR5-rs1799987, ELMO1-rs74130, and IL8-rs4073 with the development of DN among Malaysian type 2 diabetes mellitus (T2DM) patients." (PMID 30713847, 2019). "Additionally, diabetes or intraocular injection of recombinant CCL2 resulted in increased expression of the macrophage marker, F4/80." (PMID 25329075, 2014). "In diabetes, the increased expression of CCL2 and other chemokines in the retina may be due to upregulation by any or all of these cell types." (PMID 25329075, 2014). "Diabetes and CCL2 injection also induced activation of retinal microglia in these animals." (PMID 25329075, 2014). "Whereas most of the current clinical trials target the molecule VEGFα, targeting CCL2 can address the mechanisms of early leukocyte influx, leukostasis and adhesion to the retinal capillary wall in diabetes, a potentially critical upstream target for the treatment of DME." (PMID 25329075, 2014). "Thus, genetic background potentially dictates the role of CCL2 involvement in diabetes onset and progression by potentially controlling the type of leukocyte recruited and the immune response pattern initiated (e.g., Th1 vs. Th2 responses)." (PMID 23056550, 2012). "Additionally, our analysis highlighted the enhanced expression of certain inflammatory markers (e.g., CCL2 and TGFB1/2) during ED with diabetes mellitus, suggesting a pivotal role of local inflammatory responses in the early pathophysiology of diabetes-associated ED." (PMID 39766863, 2024). "The presence of metabolic syndrome or diabetes in the comparison groups was not systematically assessed, which could introduce bias given that CCL2 is implicated in these conditions." (PMID 39199602, 2024).
diabetes (continued). "Additionally, PCB118 increased the production of inflammatory factors (IL-6, IL-18, and CCL-2) that may damage islet cells, possibly leading to the occurrence and development of diabetes." (PMID 34055976, 2021). "Finally, we examined whether the injection of non-diabetic plasma reverses M1 cytokine expression, plasma DPP4 activity and CCL2 levels, systemic inflammation, and glucose intolerance in diabetes." (PMID 34043673, 2021). "Since CCL2 serves as a primary attractant of monocytes to sites of inflammation in tissues, we wanted to determine whether there is infiltration of these cells into the retina in diabetes." (PMID 25329075, 2014). "Thus, our studies indicate that retinal endothelial cells can also contribute to the increased production of the chemokine CCL2 in diabetes, although other cells like Muller cells, pericytes and microglia might contribute to this process." (PMID 25329075, 2014). "CCL2 and CXCL10 attract macrophages, and may contribute to the recruitment of immune cells during the early stages of insulitis, as suggested by the observation that transgenic expression of CCL2 in beta cells causes insulitis and diabetes." (PMID 22412385, 2012). "First, we selected the central core sites in the PPI network of AS, DN, DR and found six characteristic genes of diabetes (TYROBP, LCP2, CCL2, CD44, RPL3, CDK4)." (PMID 36755923, 2023). "Studies here extend on the prior report by demonstrating that diabetes-induced NF-κB activation and enhanced expression of CCL5 and CCL2 in the retina also require GSK3 activity." (PMID 37392853, 2023). "Under the chemotaxis of chemokines (CCL2, CX3CL1, CCL5, etc.), phagocytes such as monocytes and macrophages gather at the site of diabetes complications." (PMID 36755923, 2023). "Meanwhile, the pathways involved in the treatment of diabetes complicated by AS by XFZYD are related to the VEGFA signaling pathway, AKT1 signaling pathway, and CCL2 signaling pathway." (PMID 35960089, 2022). "Additionally, polymorphisms in C-C motif chemokine ligand 2 (CCL2) gene which codes an inflammatory or inducible chemokine and C-C motif chemokine ligand 5 (CCL5) gene which is a target of NF- B activity, have been suggested to alter the risk of post-transplant diabetes mellitus development." (PMID 33810367, 2021). "GCG, IRS1, VEGFA, STAT3, CCL2, CASP3, and APOE as diabetes mellitus-related proteins and SREBF1, LPL, PPARA, APOB, GPT, MAPK8, and FASN as NAFLD-specific proteins were identified as possible discriminating factors between the two studied diseases." (PMID 35154608, 2021). "Non-diabetic plasma reverses M1/M2 cytokine expression, plasma CCL2 levels, DPP4 activity, and Kupffer cell activation in diabetes." (PMID 34043673, 2021). "Urinary excretion of CCL2 correlates with the severity of DKD, again supporting the role of increased inflammation and renal injury in diabetes." (PMID 34925339, 2021). "Exposure of cultured podocytes to AGE, a diabetes-like condition, increased JAK2 activity and induced expression of SAA3 as well as pro-inflammatory mediators including Cxcl5, Ccl2, and Ccl5." (PMID 30763329, 2019). "Weobserved a statistically significant decrease of MCP-1/CCL2, GM-CSF, IL-5,IL-6, and IFN-γ in the saliva of patients with chronic periodontitisassociated with type 2 diabetes mellitus in comparison with patients withchronic periodontitis only." (PMID 31993238, 2019). "Previous studies have shown that another pro-inflammatory gene, chemokine (C-C motif) ligand 2 (CCL2), is overexpressed in macrophages from murine models of diabetes." (PMID 31626638, 2019). "Compared with NC, the levels of serum inflammation indexes like CRP, IL6, IL8, TNF-α, and CCL2 were significantly increased (p < 0.05), while IL10 levels were significantly decreased (p < 0.05) in diabetes groups (MC, WP and SCCOPs-treated groups)." (PMID 29316680, 2018).
diabetes (continued). "This is in good agreement with findings in diabetes-prone NOD mice, where increased expression of CCL2, CXCL10 and other chemokines/cytokines are observed in the pre-diabetic period." (PMID 22412385, 2012). "Additionally, IL-19 has been shown to modulate α-SMA expression via CCL2 and TGF-β signaling pathways in models of diabetes-induced kidney damage, contributing to fibrosis development." (PMID 40606673, 2025). "Furthermore, the enhanced expression of TLR2 contributes to the upregulation of chemokine MCP1/CCL2 in both glomeruli and tubular epithelium, potentially leading to impaired renal function in individuals with diabetes." (PMID 38094870, 2023). "Several other comorbidities, such as diabetes, hypertension, dyslipidemia, and smoking, were examined for a possible association with serum TNF-α and CCL2 levels, without any significant results." (PMID 36613708, 2022). "In MGC, diabetes induced-CD40 activation is responsible for upregulating expression of inflammatory cytokines, such as TNF-α, IL-1β, NOS, and monocyte chemoattractant protein-1 (MCP-1 or chemokine ligand 2, CCL2)." (PMID 35453302, 2022). "Analogous findings were noted in the case of plasma C-C motif chemokine ligand 2 (CCL2)/JE monocyte chemoattractant peptide-1 (JE/MCP1), which was upregulated in diabetes and at 150 or 50 ppm/day, in both male and female mice, significantly lower CCL2 was noted vs. vehicle treatment." (PMID 35562970, 2022). "Cumulative evidence suggests that the upregulation of inflammatory factors such as tumor necrosis factor-α (TNF-α), intercellular adhesion molecule-1 (ICAM-1) and monocyte chemoattractant factor-1 (MCP-1 or CCL2), and subsequent leukocyte diapedesis, contribute to the BRB breakdown in diabetes." (PMID 34200613, 2021). "Studies have reported that diabetes-induced gliosis eventually leads to the production and release by MGCs of inflammatory molecules such as interleukin-1β (IL-1β), interleukin-6 (IL-6), tumor necrosis factor-α (TNF-α), and chemokine ligand-2 (CCL2)." (PMID 34071438, 2021). "To identify the effects of diabetic and non-diabetic plasma on plasma CCL2 levels in diabetes, we harvested plasma from Leprdb/db and Lepr+/+ mice, and injected them into adipose tissue of Leprdb/db mice." (PMID 34043673, 2021). "Altogether, these results suggest that diabetes increases plasma CCL2 levels, and non-diabetic plasma possesses a suppressive effect on plasma CCL2 levels in diabetes." (PMID 34043673, 2021). "In one study, CCL2 and CXCL4 treatment accelerated the wound healing process in a diabetes model." (PMID 34444827, 2021). "miRs from the let-7 family directly diminish the expression of MCP-1/CCL2 and RANTES/CCL5 cytokines, which are complicated in the progression of BBB inflammation that happens during traumatic brain injury, various forms of encephalitis and diabetes." (PMID 32766248, 2020). "Induction of PAI-1 (total and active), IL-8, CCL2, and E-selectin in AKT2 KO cells is consistent with hyperinsulinemia and hyperglycemia in patients or with experimental animal models with diabetes and promotes recruitment of immune cells that stimulate inflammation." (PMID 31835296, 2019). "CCL2 expression, macrophage recruitment and fibrosis were all attenuated in TLR4−/− mice with diabetes.This result is consistent with a recent study in humans where over expression of TLR4 in renal tubules correlated with monocyte and macrophage accumulation in diabetic kidneys." (PMID 24842252, 2014). "Intriguingly, however, transgenic expression of CCL2 on the non-obese diabetic mouse background, a model of autoimmune-mediated islet destruction, delays diabetes development despite increased immune cell accumulation in islets." (PMID 23056550, 2012). "The discovery that p65 overexpression is sufficient to drive synthesis and secretion of CCL2 from β-cells in the absence of a pro-inflammatory stimulus has important implications for both major forms of diabetes." (PMID 23056550, 2012).